BCR (BCR activator of RhoGEF and GTPase)
Diseases named in the same sentence as BCR in open-access papers (continued):
Sharing a sentence is not in itself a finding about the gene and the disease.
myeloproliferative neoplasm (133 papers, 2010 to 2026). A clonal hematopoietic stem cell disorder, characterized by proliferation in the bone marrow of one or more of the myeloid (i.e., granulocytic, erythroid, megakaryocytic, and mast cell) lineages. "Calreticulin (CALR) mutations are prevalent in 20%-30% of patients with BCR::ABL1-negative myeloproliferative neoplasms (MPN)." (PMID 41532194, 2026). "Chronic neutrophil leukemia (CNL) is a rare BCR/ABL-negative myeloproliferative neoplasm (MPN) whose molecular biology is based on mutations in the CSF3R (Colony Stimulating Factor 3 Receptor)." (PMID 39105740, 2024). "We recently described two new disease variants we claimed belonging to the BCR::ABL-negative myeloproliferative neoplasms (MPNs) domain." (PMID 36871061, 2023). "We do so in the context of the current topography of the BCR::ABL-negative myeloproliferative neoplasms (MPNs) where two new variants are reported: clonal megakaryocyte dysplasia with normal blood values (CMD-NBV) and clonal megakaryocyte dysplasia with isolated thrombocytosis (CMD-IT)." (PMID 36871061, 2023). "CALR mutations are known drivers of myeloproliferative neoplasms and may therefore contribute to a clonal advantage and expansion even after the BCR::ABL1 clone has been eradicated." (PMID 35902731, 2022). "Chronic myeloid leukemia (CML) is a myeloproliferative neoplasm characterized by the presence of the Philadelphia chromosome that encodes for the tyrosine kinase protein BCR-ABL1 from the Breakpoint Cluster Region (BCR) sequence and the Abelson (ABL1) gene." (PMID 33466839, 2021). "Similarly, mutations in other tyrosine kinase receptors commonly associated with myeloproliferative diseases such as BCR/ABL or FLT3ITD cause increased ROS in myeloid cells." (PMID 27611333, 2016). "Chronic myeloid leukemia (CML) is a hematopoietic stem cell disorder included in the broader diagnostic category of myeloproliferative neoplasms, associated with fusion by BCR gene at chromosome 22q11 to ABL1 gene at chromosome 9q34 with the formation of the Philadelphia (Ph) chromosome." (PMID 25045550, 2014). "We aimed to evaluate their characteristics during the follow-up of BCR::ABL-negative myeloproliferative neoplasms." (PMID 41540281, 2026). "Over the past decades, significant progress has been made in our understanding of the pathophysiology of BCR::ABL1-negative myeloproliferative neoplasms." (PMID 39960584, 2026). "Chronic myeloid leukemia (CML) is a myeloproliferative neoplasm characterized by the BCR::ABL1 rearrangement, usually diagnosed by data of peripheral blood, bone marrow cytology, cytogenetics, and the detection of the BCR:ABL1 rearrangement." (PMID 41748895, 2026). "BCR::ABL-negative myeloproliferative neoplasms (MPNs) are chronic myeloid disorders that originate from the acquisition of a somatic driver mutation in one of the JAK2, CALR or MPL genes." (PMID 41540281, 2026). "Chronic myeloid leukemia (CML) is a triphasic myeloproliferative neoplasm characterized by the breakpoint cluster region-Abelson BCR::ABL1 fusion gene, typically detected by reverse transcription-quantitative polymerase chain reaction (RT-qPCR)." (PMID 41869197, 2026). "Essential thrombocythemia and primary myelofibrosis belong to the group of BCR::ABL1-negative myeloproliferative neoplasms." (PMID 39960584, 2026). "BCR::ABL1-negative myeloproliferative neoplasms are chronic diseases characterized by high symptom burden due to systemic inflammation." (PMID 41559233, 2026). "More than a decade after its discovery, advances have been made in understanding the oncogenic role of mutant CALR in BCR::ABL1-negative myeloproliferative neoplasms (MPNs)." (PMID 41228192, 2025). "BCR::ABL1‐negative myeloproliferative neoplasms (MPNs) are clonal haematopoietic stem cell disorders characterized by specific driver mutations and an increased risk of both macrothrombosis and microthrombosis." (PMID 39183370, 2024).
myeloproliferative neoplasm (continued). "Myelofibrosis (MF) is a BCR::ABL1-negative myeloproliferative neoplasm (MPN) characterized by splenomegaly, constitutional symptoms, heterogeneous blood cell alterations and bone marrow fibrosis (BMF)." (PMID 39179882, 2024). "BCR::ABL1-negative myeloproliferative neoplasms (MPNs) are clonal disorders originating from a single haematopoietic stem cell, mainly referred to as polycythaemia vera (PV), essential thrombocythaemia (ET) and primary myelofibrosis (PMF)." (PMID 38771542, 2024). "The classical BCR::ABL1-negative myeloproliferative neoplasms (MPN) form a group of bone marrow (BM) diseases with the potential to progress to acute myeloid leukemia or develop marrow fibrosis and subsequent BM failure." (PMID 38602559, 2024). "There is consensus between the classifications for BCR::ABL1-negative myeloproliferative neoplasms (MPNs) other than polycythaemia vera (PV)." (PMID 40949653, 2024). "BCR::ABL1-negative myeloproliferative neoplasms are hematopoietic disorders characterized by panmyelosis." (PMID 38654055, 2024). "Myelofibrosis (MF) is a life-threatening complication of BCR:ABL1-negative myeloproliferative neoplasms (MPNs) induced by the MPN cell clonal proliferation, leading to bone marrow fibrosis, extramedullary hematopoiesis, and acute leukemia transformation." (PMID 39470742, 2024). "Predicting the likelihood vascular events in patients with BCR/ABL1-negative myeloproliferative neoplasms (MPN) is essential for the treatment of the disease." (PMID 38776019, 2024). "Typical BCR::ABL1-negative myeloproliferative neoplasms (MPN) are mainly referred to as polycythemia vera (PV), essential thrombocythemia (ET), and primary myelofbrosis (PMF)." (PMID 38771542, 2024). "The classical BCR::ABL1-negative myeloproliferative neoplasms (MPNs) are hematopoietic stem cell disorders with the clonal proliferation of one or more types of cells of the myeloid lineage." (PMID 37745842, 2023). "This review focuses on how the use of new technologies like next-generation sequencing (NGS) helps in the diagnosis of BCR::ABL1-negative myeloproliferative neoplasms." (PMID 37745842, 2023). "Over the past decade, tremendous progress has been made in understanding the pathogenesis of BCR::ABL1-negative myeloproliferative neoplasms." (PMID 37745842, 2023). "Chronic neutrophilic leukemia (CNL) represents a rare disease, that has been classified among the BCR/ABL-negative myeloproliferative neoplasms." (PMID 35494007, 2022). "BCR::ABL1-negative myeloproliferative neoplasms (MPNs) are a group of stem cell disorders characterized by aberrant hematopoietic proliferation with an increased risk of leukemic transformation." (PMID 36611899, 2022). "Chronic myeloid leukemia (CML) is a myeloproliferative neoplasm initiated by the presence of the fusion gene BCR::ABL1." (PMID 36293127, 2022). "Chronic myeloid leukemia (CML) is a myeloproliferative disease characterized by a unique BCR-ABL fusion gene." (PMID 36430822, 2022). "CML is a myeloproliferative disease featured by the BCR-ABL fusion gene, which forms a chimeric protein with deregulated tyrosine kinase activity." (PMID 33941772, 2021). "Chronic myelogenous leukemia (CML) is a clonal myeloproliferative neoplasm resulting from BCR–ABL-transformed hematopoietic stem cells." (PMID 32165863, 2020). "Chronic myeloid leukemia (CML) is a myeloproliferative disease which uniquely expresses a constitutively active tyrosine kinase, BCR/ABL." (PMID 29559564, 2018). "Chronic myeloid leukemia (CML) is a myeloproliferative disease characterized by the presence of BCR/ABL fusion gene in leukemic cells, which promotes uncontrolled cell proliferation." (PMID 28902850, 2017). "From the Sca1+ compartment BCR/ABL is able to induce nearly exclusively myeloproliferative disease, which is characterized by a rapid onset of the disease, accumulation of mature myeloid linage cells in the spleen and BM and splenomegaly." (PMID 25919613, 2015).
myeloproliferative neoplasm (continued). "CML is a clonal myeloproliferative disorder that is characterized by the presence of the fusion oncogene, BCR-ABL." (PMID 24137469, 2013). "The lymphoma associated oncogene NPM/ALK significantly altered the expression of 91phosphopeptides whilst the myeloproliferative disorder oncogenes BCR/ABL, TEL/PDGFRβ, Kit D816V, and Fip1L/PDGFRα changed the expression of 94, 114, 111 and 68 respectively." (PMID 22745689, 2012). "The activated Jak2-V617F mutant is present in most cases of BCR/ABL-negative myeloproliferative neoplasms and constitutively activates downstream signals from homodimeric cytokine receptors, such as the erythropoietin receptor (EpoR)." (PMID 22087308, 2011). "Chronic myeloid leukemia (CML) is a clonal myeloproliferative disorder associated with chromosomal translocation between chromosomes 9 and 22, which forms a fusion gene of BCR-ABL encoding BCR-ABL fusion protein." (PMID 20199658, 2010). "According to the 2022 World Health Organization (WHO) classification for hematopoietic malignancies, major categories of BCR::ABL1-negative myeloproliferative neoplasms (MPN) include polycythaemia vera (PV), essential thrombocythaemia (ET), and primary myelofibrosis (PMF)." (PMID 40287867, 2025). "Interestingly, the phenotypic shift toward a BCR-like phenotype in response to ruxolitinib treatment was reported in a 41-year-old male with a myeloproliferative neoplasm and BCR::JAK2 gene fusion." (PMID 41009670, 2025). "Constitutive JAK/STAT pathway activation is crucial in the pathogenesis of BCR::ABL1-negative myeloproliferative neoplasms (MPN), but has not yet been linked to interferon (IFN)-γ signaling and tumor microenvironment." (PMID 40764668, 2025). "PV is a subtype of BCR/ABL1-negative myeloproliferative neoplasms (MPNs)." (PMID 40493419, 2025). "Essential thrombocythemia proved to be the most frequent myeloproliferative neoplasm, which are findings that align with the premises established by Torres15, who studied a population with BCR::ABL1-negative myeloproliferative neoplasms in the state of Amazonas (Brazil)." (PMID 38654055, 2024). "Minor revisions have been made to the diagnostic criteria for BCR::ABL1-negative myeloproliferative neoplasms." (PMID 39682300, 2024). "The classical BCR::ABL1-negative myeloproliferative neoplasms such as polycythemia vera (PV), essential thrombocythemia (ET), and myelofibrosis (MF) are clonal diseases with the presence of characteristic “driver mutations” in one of the genes: JAK2, CALR, or MPL." (PMID 37745842, 2023). "BCR::ABL1-negative myeloproliferative neoplasms (MPNs) are a group of hematopoietic malignancies in which somatic mutations are acquired in hematopoietic stem/progenitor cells, resulting in an abnormal increase in blood cells in peripheral blood and fibrosis in bone marrow." (PMID 37629188, 2023). "Chronic myeloid leukemia (CML), a rare myeloproliferative disease, is associated with chromosomal translocation (i.e., Philadelphia chromosome), which encodes BCR::ABL1 oncoprotein, through the fusion of BCR and ABL1 genes, with active tyrosine kinase activity." (PMID 37358999, 2023). "BCR::ABL1-negative myeloproliferative neoplasms (MPNs) include three major subgroups—polycythemia vera (PV), essential thrombocythemia (ET), and primary myelofibrosis (PMF)—which are characterized by aberrant hematopoietic proliferation with an increased risk of leukemic transformation." (PMID 36611899, 2022). "Myelofibrosis (MF) is a breakpoint cluster region protein (BCR)-Abelson tyrosine-protein kinase (ABL)–negative myeloproliferative neoplasm (MPN) and represents a group of tumors caused by abnormal proliferation of one or more myeloid cells." (PMID 32333155, 2020).
myeloproliferative neoplasm (continued). "The annual incidence of BCR-/ABL1-negative myeloproliferative neoplasms (MPN), namely polycythemia vera (PV), essential thrombocythemia (ET), and primary myelofibrosis (PMF) in the western world, is estimated to be maximum 2.8, 2.3, and 1.5 cases per 100.000 population, respectively." (PMID 31781224, 2019). "Inflammatory and oncogenic signaling converge in disease evolution of BCR–ABL-negative myeloproliferative neoplasms, clonal hematopoietic stem cell disorders characterized by gain-of-function mutation in JAK2 kinase (JAK2V617F), with highest prevalence in patients with polycythemia vera (PV)." (PMID 30967632, 2019). "For example, the translocation generating BCR-ABL can drive a myeloproliferative disease (CML) apparently without other driver mutations." (PMID 31034356, 2019). "In addition to MLN-eo-TK, JAK2 rearrangements can also be found in BCR::ABL1-negative myeloproliferative neoplasms (MPN), myelodysplastic neoplasms (MDS), MDS/MPN overlap syndromes, B/T lymphomas, acute myeloid (AML), lymphoblastic (ALL) or mixed- phenotype acute leukemia (MPAL)." (PMID 41530508, 2026). "The classical BCR::ABL1-negative myeloproliferative neoplasms (MPN) include the subtypes essential thrombocythemia (ET), polycythemia vera (PV), and primary myelofibrosis (PMF)." (PMID 38602559, 2024). "Myelofibrosis (MF) is a chronic, BCR::ABL–negative myeloproliferative neoplasm (MPN) that is characterized by changes in blood counts, splenomegaly, disease-associated symptoms, and bone marrow (BM) fibrosis." (PMID 37792065, 2023). "The JAK2V617F variant constitutes a genetic alteration of higher frequency in BCR/ABL1 negative chronic myeloproliferative neoplasms, which is caused by a substitution of a G ˃ T at position 1849 and results in the substitution of valine with phenylalanine at codon 617 of the polypeptide chain." (PMID 35204792, 2022). "The search yielded nine cases of coexistent MPN and LPD out of a total of 269 patients diagnosed with BCR-/ABL1-negative MPN or an MDS/MPN (myelodysplastic syndrome/myeloproliferative neoplasms) and 1062 patients diagnosed with an LPD." (PMID 31781224, 2019). "BCR::ABL1-negative myeloproliferative neoplasms (MPN) comprise a heterogeneous group of hematological neoplastic diseases that is characterized by cytosis of one or more cell lineages in the peripheral blood, associated with a significant risk of developing a secondary acute myeloid leukemia (sAML)." (PMID 40764668, 2025). "In this review, we summarize molecular drug resistance biomarkers in targeted therapies in BCR::ABL1-driven chronic myeloid leukemia (CML) and JAK2-driven myeloproliferative neoplasms (MPNs)." (PMID 39104388, 2024). "In the 2008 WHO classification, myeloproliferative disorders initially called ‘Chronic MyeloProliferative Diseases’ (CMPD) were reclassified as ‘MyeloProliferative Neoplasms’ (MPN) with nine entities and were split into BCR::ABL1-positive MPN (CML) and BCR::ABL1-negative MPN." (PMID 36980287, 2023). "This genetic alteration leads to the production of an oncoprotein BCR::ABL1 with constitutively active ABL1 tyrosine kinase activity, whose deregulated action is responsible for the development of this myeloproliferative neoplasm." (PMID 37444494, 2023). "Chronic myeloid leukemia (CML), originating from a constitutively active tyrosine kinase, BCR/ABL1 which occurs spontaneously, is a myeloproliferative disease affecting older adults typically." (PMID 29559564, 2018). "The classical BCR::ABL1 negative myeloproliferative neoplasms are a group of blood disorders characterized by the overproduction of mature blood cells in the bone marrow." (PMID 39960584, 2026). "To collect evidence that supports this idea, we considered our previous findings that the Alox5 gene plays an essential role in functional regulation of LSCs for both PV and CML, two different types of myeloproliferative neoplasms driven by JAK2V617F and BCR-ABL, respectively." (PMID 41226393, 2025).
myeloproliferative neoplasm (continued). "The study cohort of 74 patients with BCR/ABL negative myeloproliferative disorders included essential thrombocythemia, polycythemia vera, and primary myelofibrosis (PMF)." (PMID 38776019, 2024). "Chronic neutrophilic leukemia (CNL) is a rare but potentially aggressive BCR::ABL1 negative myeloproliferative neoplasm, characterized by sustained mature, neutrophilic leukocytosis." (PMID 36568246, 2022). "Chronic neutrophilic leukemia (CNL) is a rare BCR-ABL negative myeloproliferative neoplasm that usually affects older adults with a poor prognosis." (PMID 36210951, 2022). "It is a myeloproliferative disease characterized by the presence of a molecular rearrangement, known as the Philadelphia chromosome (Ph), that generates a BCR/ABL fusion gene and the production of the BCR/ABL fusion protein with tyrosine kinase activity." (PMID 36615316, 2022). "Primary myelofibrosis (PMF) is a kind of breakpoint cluster region protein (BCR)-Abelson tyrosine-protein kinase (ABL)–negative myeloproliferative neoplasm (MPN) resulted from the clonal proliferation of abnormal hematopoietic stem cells." (PMID 33386934, 2021). "Although the dual BCR-ABL/SRC TKI dasatinib inhibits the kinase activity of KIT D816V in vitro and has demonstrated efficacy in other myeloproliferative neoplasms, such as CML, it has displayed minimal activity in patients with SM." (PMID 26002753, 2015). "The clonal composition of myeloproliferative neoplasms (MPN) harboring both JAK2 V617 F and BCR::ABL1 and the outcomes of these patients are unclear and management remains challenging." (PMID 40299271, 2025). "Chronic myeloid leukemia (CML) and Philadelphia (Ph)-negative myeloproliferative neoplasms (MPN) are generally distinct clonal disorders, with the co-occurrence of BCR::ABL1 rearrangement with concomitant Ph-negative MPN rarely reported." (PMID 41896663, 2026). "On account of the clinical picture and absence of a BCR::ABL1 fusion, she was diagnosed with a Philadelphia-negative myeloproliferative neoplasm and treated accordingly with hydroxycarbamide." (PMID 37496024, 2023).